C2CD2 (C2 calcium dependent domain containing 2)
Synonyms: C21orf25; C21orf258; TMEM24L; DKFZP586F0422
Tractability: Antibody: UniProt predicts a signal peptide or a membrane-spanning region. PROTAC: ubiquitination databases record sites on it; its protein half-life has been measured.
Gene: Protein-coding gene on chromosome 21 (41,885,112 to 41,954,018, reverse strand). Ensembl gene ENSG00000157617.
Subcellular location: Membrane
Subcellular location (Human Protein Atlas): Nucleoplasm
Gene Ontology:
Cellular component: cytosol; nucleus; membrane
Genetic constraint (gnomAD): Loss-of-function variants: 37 observed, 52.69 expected, observed/expected ratio (o/e) 0.7, 90% interval 0.54 to 0.92. The upper end of that interval is the gene's LOEUF score, 0.92, which puts it in group 3 of 6, group 1 being the genes least tolerant of losing a copy. Missense variants: 720 observed, 779.16 expected, observed/expected ratio (o/e) 0.92, 90% interval 0.87 to 0.98. Synonymous variants: 377 observed, 335.15 expected, observed/expected ratio (o/e) 1.12, 90% interval 1.03 to 1.23.
Homologues: Orthologues: chimpanzee C2CD2 (98% identical), macaque C2CD2 (94% identical), pig C2CD2 (77% identical), dog C2CD2 (76% identical), rat C2cd2 (72% identical), mouse C2cd2 (72% identical), rabbit C2CD2 (70% identical), guinea pig C2CD2 (67% identical), tropical clawed frog c2cd2 (49% identical), zebrafish c2cd2 (40% identical), Drosophila melanogaster CG10737 (18% identical), Caenorhabditis elegans tmem-24 (16% identical). Paralogues in human: C2CD2L (29% identical).
Diseases named in the same sentence as C2CD2 in open-access papers:
C2CD2 is named in the same sentence as 1 disease in open-access papers, as found by Europe PMC text mining. Sharing a sentence is not in itself a finding about the gene and the disease. The quoted sentences say what the papers report.
breast carcinoma (1 paper, 2024). "C2CD2 is a prognostic biomarker for breast cancer in bioinformatics." (PMID 39770478, 2024).